RN7SL804P (RNA, 7SL, cytoplasmic 804, pseudogene)
Gene: Miscellaneous RNA gene on chromosome 12 (69,400,903 to 69,401,200, forward strand). Ensembl gene ENSG00000266185.
Homologues: Orthologues: chimpanzee Metazoa_SRP (99% identical), macaque Metazoa_SRP (94% identical). Paralogues in human: RN7SL1 (85% identical), RN7SL2 (85% identical), RN7SL3 (84% identical), RN7SL797P (84% identical), RN7SL451P (82% identical), RN7SL664P (82% identical), RN7SL712P (82% identical), RN7SL44P (82% identical), RN7SL15P (82% identical), RN7SL665P (82% identical), RN7SL147P (81% identical), RN7SL408P (81% identical), and 702 more.